LINC01431 (long independently transcribed non-coding RNA 1431)
Gene: Long non-coding RNA gene on chromosome 20 (23,356,585 to 23,358,280, reverse strand). Ensembl gene ENSG00000232645.
Diseases named in the same sentence as LINC01431 in open-access papers:
LINC01431 is named in the same sentence as 1 disease in open-access papers, as found by Europe PMC text mining. Sharing a sentence is not in itself a finding about the gene and the disease. The quoted sentences say what the papers report.
tumor (1 paper, 2022). "In line with in vitro data, RT‐qPCR analysis of HCC para‐tumor tissues displayed a markedly positive correlation between ZHX2 and LINC01431 expression, and the levels of pgRNA in HCC patients with ZHX2lowLINC01431low were significantly higher than those in ZHX2hiLINC01431hi patients." (PMID 35398991, 2022).